IL10 (interleukin 10)
Diseases named in the same sentence as IL10 in open-access papers (continued):
Sharing a sentence is not in itself a finding about the gene and the disease.
infection (continued). "Other studies from the same group found no significant changes in IL-10 levels after immunisation or challenge infections with different ASFV strains." (PMID 35215216, 2022). "The only significant difference was observed between the infection with the mutant strain cultured in dextrose (MSD) and the same strain cultured in lipids in the exponential phase (MEL), the latter presenting the lowest levels of IL-10." (PMID 35873160, 2022). "Our data showing a reduced impact of IL-10 in the established memory response are in line with our previously published data demonstrating that IL-10 overexpression during the chronic stage of Mtb infection does not impact the outcome of infection." (PMID 35935958, 2022). "We found that unopposed PPARγ activation suppresses bacterial clearance and blunts the induction of proinflammatory (but not anti-inflammatory, IL10) cytokines and ROS in response to infection both in vivo and in vitro." (PMID 35288651, 2022). "First, they used tiger IL-10 GFP-reporter mice to determine that NK cells from the blood and lung, but not other lung cells, are the main source of IL-10 after 72 h of intranasal infection with sublethal doses of S. pneumoniae." (PMID 35053151, 2021). "However, CD4+ T cells primed and differentiated in an IL-10–enriched environment displayed reduced expression of CXCR3 and, because they did not migrate into the lung parenchyma, their ability to control infection was limited." (PMID 34554927, 2021). "On the other hand, IL-10 overexpression induced during the chronic phase of infection significantly altered neither progression nor control of M. tuberculosis." (PMID 34554927, 2021). "Interestingly, IL-10+CD4+ and IL-10+CD8+ heart T cells were increased in mice treated with anti-IL-2 mAb during this phase of the infection compared to control infected rat IgG-treated mice." (PMID 34869064, 2021). "By contrast, localized infection with intranasal instillation of influenza virus and the attenuated Yersinia pestis strain resulted in NK cells producing IFNγ but not IL-10." (PMID 35053151, 2021). "As the IL-10 cytokine is not effective in resolving the infection it progressed to the chronic form." (PMID 34732154, 2021). "IL-10 overexpression early during infection did not, we found, significantly impair the kinetics of CD4+ T cell priming and effector differentiation." (PMID 34554927, 2021). "During the early stages of infection, IL-10 overexpression altered neither populations of antigen-presenting cells (APCs) in the mediastinal lymph nodes (MLNs) nor the kinetics of CD4+ T cell activation." (PMID 34554927, 2021). "However, following treatment among children with natural infection in this cohort, PBMC stimulation in response to SWAP and SEA resulted in significant increases in the production of IL-4, IL-5, IL-10, and IL-13 compared to uninfected children." (PMID 33861768, 2021). "IL-10 has a central role in limiting inflammation and inhibiting CD4+ T cell-mediated severe immunopathology, and IL-4 functions to enhance IFN-γ production in the late stage of infection." (PMID 33087183, 2021). "However, 2 days post-infection with V. anguillarum, 2 % of ARA increased the expression of il-1β and cox2 genes and 4 % increased il-10 expression." (PMID 36420498, 2021). "Importantly, IL-10 exerted quantitatively stronger regulatory effects on innate and CD4+ T cell responses during primary and secondary infections, respectively." (PMID 34414129, 2021). "Interestingly however, despite the high levels of IL-10, IFN-γ–producing CD4+ T cells increased rapidly in the lungs of pMT-10 mice after day 30 after infection." (PMID 34554927, 2021). "PBMCs, isolated from healthy people from non-endemic region, upon LmCen−/− infection also induced more IFN-γ compared to IL-10, consistent with our immunogenicity data in LmCen−/− immunized hamsters." (PMID 34330999, 2021).
infection (continued). "However, the presence of IL-10 and TGFβ, and the later increase of VEGF suggests that there are M2 MΦ involved in controlling the acute phase of infection." (PMID 34832600, 2021). "However, there was a sharp increase in IL-10 at 26 WPI, with levels higher than those pre-infection, in cattle that showed the greatest severity of disease." (PMID 33746980, 2021). "Here, we identify the tricarboxylic acid (TCA) cycle metabolite fumarate as the driver of IL-10 during macrophage infection with H. capsulatum in the absence of HIF-1α." (PMID 34749531, 2021). "Moreover, virus mixed infection enhanced the mRNA expressions of TNF-α, IL-1β, IL-6, IL-10, IFN-α, and IFN-β by 2–170 times." (PMID 33827620, 2021). "Meanwhile, GL or GM pre-infection treatments significantly (P < 0.05) decreased ST-induced pro-inflammatory cytokine (IFN-γ, TNF-α, and IL-6) expression in both spleen and liver and increased (P < 0.05) anti-inflammatory cytokine IL-10 secretion in spleen." (PMID 34239908, 2021). "In addition, the levels of IL-10 of MDR-MTB and H37Rv group at 4~48 h were lower than that of the infection group (P<0.05)." (PMID 35003120, 2021). "Hepatic stellate cells regulate the immune response through anti-inflammatory cytokines, mostly IL-10 and transforming growth factor-beta (TGF-β), which are produced either in direct response to infection or to increased TNF-α in the surrounding microenvironment." (PMID 33916346, 2021). "Moreover, in ovo infection with avian metapneumovirus subtype C resulted in significant increase in IFN-γ and IL-10 gene expression in URT at 4 dpi (day of hatch) and 9 dpi (5 days post-hatch)." (PMID 34327060, 2021). "Although the authors were able to eliminate IL-10-producing NK cells in the NKp46-Cre-Il10fl/fl mice, the levels of IL-10 were not altered in the serum at day 4 post-infection, indicating another source of IL-10 in this model during acute MCMV infection." (PMID 35053151, 2021). "Interleukin-10 and TNF-α in infected cells increased relative to uninfected AMs in all treatment groups including the control foals, suggesting an age-related increase in response to infection." (PMID 33510265, 2021). "We found similar bacterial loads in B6 and pMT-10 MLNs at days 12 and 16 after infection, showing that IL-10 did not impair the transport of the bacteria from the lung to the MLN." (PMID 34554927, 2021). "Interestingly, cytokines like IL-4 (DF vs DSS, p<0.01), IL-8 (DF vs DHF, p<0.05 and DF vs DSS, p<0.05), and IL-10 (DF vs DHF, p<0.0001 and DF vs DSS, p<0.01) had significant upregulation in acute phase of infection (DF) than the DHF and DSS." (PMID 34447698, 2021). "The production of cytokines associated with pregnancy complications (premature birth and infections of the placental/fetal unit) was also increased in L. monocytogenes-infected trophoblasts (CCL2, CCL3, IL-8, CSF2, IL-1α/β, IL-1RA, IL-10, GM-CSF, IL-6, and TNFα)." (PMID 34367171, 2021). "Some authors reported significant production after infection of moDCs or bmDCs, while others reported either a non-significant induction of this cytokine or that IL-10 production was strain-dependent." (PMID 34394113, 2021). "In B6.Il10-/- mice, L. donovani infection induced a faster but transient activation of bone marrow monocytes, which correlated with the magnitude of CD4+ T cell production of IFNγ and resolution of the infection." (PMID 34557190, 2021). "Using a model of IL-10 GFP-reporter mice, they first found that NK cells in the peripheral blood are the major producers of IL-10 GFP during the early stages of MCMV infection, with a peak observed on day 4 post-infection." (PMID 35053151, 2021). "Similarly, human infection show strong cytokine production, including IL-6, IL-8, IL-12, TNF-α, CSF2, IFN-γ, IL-10, CCL2, CCL3, CCL4, and CCL714–16." (PMID 34615921, 2021).
infection (continued). "After the infection with GTP viruses (GTPV) and PPR viruses (PPRV), cytokines such as TNF-α, IL-1β, IL-6, IL-10, IFN-α, and IFN-β might regulate their replication in vitro." (PMID 33827620, 2021). "In line with this, in HFHS animals we observed increases in serum IL-10 and IL-6 levels after infection, but these were not significant and more in-depth characterization is required to establish if the cytokine response in serum truly is affected." (PMID 34960775, 2021). "In addition, reports in the literature have shown that IL-10 and TLR2 knockout mice are highly resistant to infection by Leishmania spp." (PMID 34248935, 2021). "IL10 and CTLA4 downregulate immune responses in long standing infections." (PMID 33659002, 2021). "At 12 h post-infection, total cellular RNAs were extracted and the viral RNA accumulation as well as the mRNA levels of 5 inflammatory cytokines, such as IL-6, IL-1β, TNF-α, TGF-β and IL-10, were examined using qRT-PCR." (PMID 34335977, 2021). "This suggests a complex role for Dectin-1 in immune defense against A. fumigatus, with Dectin-1 on non-hematopoietic (presumably epithelial) cells providing control of infection via IFN-γ and IL-10 production and Dectin-1 on hematopoietic cells driving an IL-17 mediated response." (PMID 33575235, 2021). "Here we also show that IL-10 production after infection is important to reduce lung histopathology but has negative impact on the ability of the mouse immune system to control bacterial burden." (PMID 33995357, 2021). "This translated into a significantly higher ratio of IFN-γ to IL-10 in LmCen−/− immunized animals compared to nonimmunized animals consistent with the immunological control of infection in cured VL patients." (PMID 34330999, 2021). "In both non-CF and CF mice, there is a significant increase in IL-10 serum concentrations at 48 h post-infection (p = 0.050, p = 0.024)." (PMID 34475490, 2021). "Our data showed that whereas all non-transferred WT mice survived until the end of the experiment and had a low clinical score, non-transferred Il10-/- mice had the highest clinical score and 100% mortality at day 4 post-infection." (PMID 33995357, 2021). "In stark contrast with these data, IL-10 overexpression after the onset of the T cell response did not impact the outcome of infection." (PMID 34554927, 2021). "In contrast with these studies, we did not observe significant DCA-inhibiting effects on IL-1β, IL-10 and IL-6 secretion by Stm- or Mtb-infected human macrophages, possibly because infection alone already strongly skewed the cytokine response." (PMID 34552598, 2021). "Additionally, immunization with centrin-deleted L. donovani resulted in CD200/CD200R downregulation and consequently suppression of IL-10-producing CD4+ T cells and more Th1 cells compared to WT infection." (PMID 33776999, 2021). "Interleukin 6 (IL-6), interleukin 10 (IL-10), and monocyte chemoattractant protein 1 (MCP-1) were induced by infection of both the wild type and complemented strains; however, they were present at significantly lower concentrations in the lungs of mice infected with the dnj1∆ mutant." (PMID 34566931, 2021). "The patterns of response of some cytokines, such as IFN-γ and IL-12p70, were most abnormal for infection in BS0–II disease, whereas for others, such as IL-10 and TNF-α, the relationships between cytokines and markers of perfusion were most abnormal for infection in BSV–VI disease." (PMID 33723589, 2021). "Here, we show that after adjusting for sex and infection, lower BE and higher lactate (biochemical markers of decreased perfusion), and worse Sarnat scores (functional outcome) all relate to lower VEGF and higher tau, GFAP, and IL-10." (PMID 34795631, 2021). "In ZC-4-infected piglets, IL-10 levels were elevated at 48 h post infection but not at other time points; in piglets in the non-toxigenic group, IL-10 levels were not elevated at any time points." (PMID 33665221, 2021).
infection (continued). "Although no statistically significant changes occurred with IL-6 or IL-10, both cytokines were correlated over the course of infection." (PMID 33483492, 2021). "Amounts of IL-10, known for its anti-inflammatory properties during infection, did not change significantly in WT animals during the course of infection." (PMID 33753412, 2021). "Besides, increased serum IL-10 level and IFN-γ during the acute phase of the infection are also in line with the previous findings." (PMID 34460819, 2021). "Specifically, it is known that a low-dose infection of ~20 T. muris eggs will proceed to chronicity, even in normally resistant strains of mouse, leading to an IFN-γ/Th17-driven disease that is controlled by a concomitant IL-10 response." (PMID 34078488, 2021). "The observed increase in IL-2 and IL-10 production, concomitantly with a reduction in IFN-γ and IL-17 levels on the 19th day of infection, could indicate expansion of Treg cells as already described in response to C. albicans." (PMID 34575795, 2021). "As infection wanes and the concentration of viral particles decreases, the IL-10 is available to bind to IL-10R and activate negative immune regulation." (PMID 33680987, 2021). "Terms that are related to inflammation included chronic inflammation, T cells, macrophages, immune response, infection, neutrophils, NF-kappa B, IL-6, B-cells, Cox-2, IFN-gamma, immunomodulation, IL-10, IL-8, lymphocytes, NF-kappa-B, neutrophil, cytokines, and chemokines." (PMID 34490346, 2021). "THP-1, THP-FAKi (THP-1 treated with FAK inhibitor) and THP-FAK+ (THP-1 overexpressing FAK) macrophages were infected with Mtb and culture supernatants were collected at 24 hours post-infection to quantify the levels of TNF-α, IL-1β and IL-10 using the solid-phase sandwich ELISA." (PMID 34745115, 2021). "Prior to infection, DP T cells showed higher TNF-α, IL-10, MIP-1β, and IL-22 expression than traditional CD4 and CD8 T cells, suggesting that these cells may potentially perform a non-specific function in the pulmonary immune response." (PMID 34929014, 2021). "The inhibitory effect of IL-10 on HIV replication has been previously reported, where IL-10 did not decrease susceptibility to infection, but exhibited antiviral effect by limiting virus production." (PMID 34432853, 2021). "Following infection, there is a shift towards lower pro-inflammatory reaction by higher levels of IL10 and TGFβ, and an increase in FoxP3 negative Treg co-expressing IL10, IFNγ, and TNF." (PMID 34684226, 2021). "Using randomly selected clinical isolates to infect THP-1 macrophages (five from early infections and five from chronic infections), we then measured mRNA levels of IL-1β, TNF, IL-8, and IL-10 through quantitative reverse transcription polymerase chain reaction (qRT-PCR) analysis." (PMID 33664232, 2021). "LMP-1 may contribute to immune suppression at an early stage of infection by blocking the secretion of IFN-α and increasing the transcription of the anti-inflammatory cytokine IL-10." (PMID 34439137, 2021). "Bx795 abolished the induction of type-I/III IFNs, CXCL10, and TNF due to PVSRIPO infection; induction of IL-1β, IL-6, and IL-10 was not affected." (PMID 33767151, 2021). "The control of the local secretion of IL-10, would favor the ability of IFN-γ to activate the leishmanicidal capacities of Leishmania-infected macrophages and, therefore, contribute to the control of infection at the site of challenge." (PMID 33673117, 2021). "ConA-stimulated splenocytes (used as a marker of systemic immunity and a surrogate to confirm successful infection) from H. diminuta+DNBS-treated mice produced more il-10 than those from non-infected or DNBS-only treated mice." (PMID 34517928, 2021). "During the early stages of infection, IL-10 overexpression altered neither DC populations in MLN nor the kinetics of CD4+ T cell activation." (PMID 34554927, 2021).
infection (continued). "It was also reported that plasma concentrations of IL-10, IL-12, and IFN-γ, were higher in patients than in family members and control individuals implying that disease processes following infection are important to induce immune activation and cytokine production." (PMID 34351903, 2021). "It was also shown that the production of KC, IL-10, IL-6, TNF-α, and IL-1β was significantly enhanced when bacterial loads were also significantly increased after S. pneumoniae infection at 7 days after H9N2 virus (A/Duck/Hong Kong/702/1979) infection." (PMID 33722928, 2021). "At 4 h post-infection, MDR-PA-challenged CHME-3 cells showed their highest mRNA expression (8.8-fold vs. 5.2 fold, p = 0.01) of IL-10, compared to cells infected with S-PA, indicating a suppression or dampening of the immune response, leading to alteration of pro- and anti-inflammatory cytokines." (PMID 32423093, 2020). "Interestingly, in CD-derived MoDC, the ratio between the amount of IL-1β, IL-23 and IL-10 and the number of intracellular LF82 cells after 24 h of infection was significantly higher compared to HD-derived MoDC, while IL-12 levels were significantly lower." (PMID 32752244, 2020). "Finally, C. psittaci infection induced robust expressions of type Th2 cytokines interleukin (IL)-4 and IL-10, while interferon gamma (IFN-γ) and tumor necrosis factor-α (TNF-α) displayed a significant decrease compared to H9N2 infection alone at 24 hpi." (PMID 32326284, 2020). "Subsequent work found that TLR7 promotes a rapid wave of IL-10 secretion from CD4 T cells that inhibits early FV replication as well as a non-neutralizing IgM response within days of infection." (PMID 33202596, 2020). "At the infection site, we detected a small production of IL-10, but we were unable to detect production of either IL-4 or interferon-γ, indicating resolution of infection without effect on the percentage of regulatory T cells." (PMID 32867857, 2020). "Here we found a detrimental increase in Cd4 / Il6 / Il10 expression in heart tissue of BALB/c mice infected with the Y strain, not observed in the absence of SLAMF1, in which Cd8 was increased at the LA phase likely allowing a better control of the infection." (PMID 32925918, 2020). "Since studies had reported that NH/P68 induced enhanced cytokine gene expression or production in macrophages compared to a virulent isolate, cytokine gene (IL-1β, IL-6, IL-10, IL-12p40, IL-18, TNF-α) expression in moMΦ after NH/68 or 22653/14 infection were monitored over-time." (PMID 32178332, 2020). "Subsequently, we sought to examine the influence of Ss infection on the systemic levels of Type-1 (IFN-γ, TNF-α, and IL-2), Type-17 (IL-17A and IL-22), Type-2 (IL-4, IL-5, and IL-13), regulatory (IL-10) and pro-inflammatory cytokines (IL-1α, IL-1β, IL-6, IL-12, and GM-CSF) in INF and UN individuals." (PMID 33042134, 2020). "When PBMCs were treated with heat-killed Mhp cells, the proinflammatory cytokines (TNF-α, IL-1β, IL-8, and IL-18) and anti-inflammatory cytokine (IL-10) were up-regulated; at the same time, the level of antigen-specific IFN-γ and IL-10 were gradually decreased during infection." (PMID 33117335, 2020). "By analysing cytokines associated with the major CD4+ve Thelper (Th) cell subsets (Interferon-gamma (IFN-γ)/Th1; Interleukin (IL)-4/Th2; IL-17A/Th17; IL-10/Tregulatory), we show that there is selective activation of PBMC producing IFN-γ and/or IL-10 during the latent phase following infection." (PMID 32487248, 2020). "Therefore, secondary abiotic IL-10−/− mice were perorally infected with C. jejuni and intraperitoneally treated with synthetic NAP from day 2 until day 5 post-infection." (PMID 32466564, 2020). "TGF-β transcription increased upon infection of IL-10 KO mice, while no changes were observed in WT mice." (PMID 33072115, 2020). "While no statistically significant changes occurred with IL-6 or IL-10, both cytokines were correlated over the course of infection." (PMID 32818217, 2020).